PARD3B (par-3 family cell polarity regulator beta)
Description:
Putative adapter protein involved in asymmetrical cell division and cell polarization processes. May play a role in the formation of epithelial tight junctions.
Synonyms: ALS2CR19; PAR3B; PAR3L; PAR3beta
Tractability: PROTAC: ubiquitination databases record sites on it.
Safety:
Unwanted effects reported when the protein is acted on. In parentheses: how it was acted on, where the effect was seen, and who reports it.
Drug Toxicity (source: ClinPGx)
Gene: Protein-coding gene on chromosome 2 (204,545,475 to 205,620,162, forward strand). Ensembl gene ENSG00000116117.
Subcellular location: Endomembrane system; Cell junction; Cell junction, tight junction
Subcellular location (Human Protein Atlas): Cell Junctions
Gene Ontology:
Molecular function: protein binding; phosphatidylinositol binding
Biological process: cell adhesion; establishment of cell polarity; establishment or maintenance of epithelial cell apical/basal polarity; intracellular protein localization; microtubule cytoskeleton organization
Cellular component: cell junction; protein-containing complex; adherens junction; apical junction complex; apical plasma membrane; cell cortex; anchoring junction; bicellular tight junction; endomembrane system
Genetic constraint (gnomAD): Loss-of-function variants: 80 observed, 105.61 expected, observed/expected ratio (o/e) 0.76, 90% interval 0.63 to 0.91. The upper end of that interval is the gene's LOEUF score, 0.91, which puts it in group 3 of 6, group 1 being the genes least tolerant of losing a copy. Missense variants: 1,477 observed, 1,397 expected, observed/expected ratio (o/e) 1.06, 90% interval 1.01 to 1.1. Synonymous variants: 531 observed, 512.02 expected, observed/expected ratio (o/e) 1.04, 90% interval 0.96 to 1.11.
Homologues: Orthologues: chimpanzee PARD3B (99% identical), macaque PARD3B (97% identical), rabbit PARD3B (90% identical), dog PARD3B (90% identical), pig PARD3B (90% identical), rat Pard3b (85% identical), mouse Pard3b (84% identical), guinea pig PARD3B (74% identical), tropical clawed frog pard3b (58% identical), zebrafish pard3bb (28% identical), Drosophila melanogaster baz (24% identical), Caenorhabditis elegans par-3 (23% identical), and 1 more. Paralogues in human: PARD3 (41% identical).
Diseases named in the same sentence as PARD3B in open-access papers:
PARD3B is named in the same sentence as 27 diseases in open-access papers, as found by Europe PMC text mining. Sharing a sentence is not in itself a finding about the gene and the disease. The quoted sentences say what the papers report.
colon cancer (4 papers, 2022 to 2025). "Previous studies reported the roles of PARD3B in neoplasms of colon cancer and CNS embryonic tumors." (PMID 36013056, 2022).
colorectal cancer (4 papers, 2019 to 2025). A primary or metastatic malignant neoplasm that affects the colon or rectum. "In colorectal cancer, PARD3B can enhance survival of cancer cells through downregulating the Lkb1-adenosine-monophosphate-activated protein kinase (AMPK) signaling pathway." (PMID 36013056, 2022). "Higher expression of PARD3B is associated with colorectal cancer malignancy and poor survival, as PARD3B inhibits Lkb1/AMPK signaling pathway and its knockout induces apoptosis and reduces proliferation, supporting its role in colorectal cancer cell survival." (PMID 31748686, 2019). "In addition, PARD3B may contribute to the oncogenesis of colorectal cancer and CNS embryonal tumors." (PMID 36013056, 2022).
AIDS (3 papers, 2012 to 2017). A syndrome resulting from the acquired deficiency of cellular immunity caused by the human immunodeficiency virus (HIV). "The significant SNP on BTA 2 was located close to gene PARD3B, which has been implicated in protection against disease progression in patients affected by the human immune deficiency virus and acquired immune deficiency syndrome (HIV/AIDS)." (PMID 28335717, 2017). "For PARD3B, a significant correlation has been found between the rare T allele for SNP rs10185378 (a missense mutation in the coding region) and slower AIDS progression." (PMID 23217182, 2012).
Obesity (3 papers, 2012 to 2020). Accumulation of substantial excess body fat. "Navigating syntenic regions suggests obesity candidate genes on chromosome 2 that are previously known to be associated with obesity-related diseases: MRPL33, PARD3B, ERBB4, STK39, and ZNF385B." (PMID 23253381, 2012). "A comparative genomic study of pigs and humans reported that PARD3B may be a candidate gene for obesity in humans." (PMID 33292532, 2020).
glioblastoma (1 paper, 2022). The most malignant astrocytic tumor (WHO grade IV). "Human U87 MG glioblastoma cells were exposed to 100 nM testosterone for 24 h, which caused a significant 115% induction in expression of PARD3B mRNA." (PMID 36013056, 2022). "After exposure to 100 nM testosterone for 12, 18, and 24 h, levels of PARD3B mRNA in U87 MG glioblastoma cells were significantly increased by 60%, 85%, and 105%, respectively." (PMID 36013056, 2022). "Exposure of U87 MG glioblastoma cells to 75 and 100 nM testosterone for 24 h led to 50% and 96% augmentations of PARD3B mRNA, respectively." (PMID 36013056, 2022). "RNA analyses were carried out to determine the roles of the testosterone AR signaling axis in regulating PARD3B gene expression in human glioblastoma cells." (PMID 36013056, 2022). "Regarding the mechanisms, exposure of human glioblastoma cells to testosterone induced AR and PARD3B gene expressions and successively stimulated cell proliferation and colony formation." (PMID 36013056, 2022). "Suppressing AR activity concurrently resulted in significant attenuations of testosterone-induced PARD3B gene expression, cell proliferation, and colony formation in human glioblastoma cells." (PMID 36013056, 2022). "Treatment of human U87 MG glioblastoma cells with 100 nM testosterone for 6 h induced PARD3B mRNA expression by 50%." (PMID 36013056, 2022). "Our in vitro results showed that suppressing the AR activation concurrently alleviated the testosterone-induced PARD3B mRNA expression, cell proliferation, and colony formation in human glioblastoma cells." (PMID 36013056, 2022). "Reducing AR activation by enzalutamide simultaneously inhibited testosterone-induced PARD3B mRNA expression in human glioblastoma cells." (PMID 36013056, 2022). "An RNA analysis further showed that exposure of human U87 MG and GBM8401 glioblastoma cells to testosterone induced expression of PARD3B mRNA in concentration- and time-dependent manners." (PMID 36013056, 2022). "After exposure to testosterone, levels of PARD3B in human glioblastoma cells were induced." (PMID 36013056, 2022). "Treatment of human U87 MG glioblastoma cells with testosterone at 25 nM for 24 h caused a slight (17%) but non-significant induction in levels of PARD3B mRNA." (PMID 36013056, 2022). "However, when the concentration of testosterone reached 50 nM, expression of PARD3B mRNA was significantly increased by 33% in human glioblastoma cells." (PMID 36013056, 2022). "Moreover, our evidence from in vitro models further proved that exposure of human U87 MG and GBM8401 glioblastoma cells, respectively derived from Caucasian and Asian cases, to testosterone induced PARD3B mRNA expression in concentration- and time-dependent manners." (PMID 36013056, 2022). "Treatment with testosterone induced expression of the PARD3B gene in human U87 MG and GBM8401 glioblastoma cells." (PMID 36013056, 2022).
intrahepatic cholangiocarcinoma (1 paper, 2025). A carcinoma that arises from the intrahepatic bile duct epithelium in any site of the intrahepatic biliary tree. "VIRMA can maintain the stability of TMED2 and PARD3B through m6A HuR mediation, activate the Akt/GSK/β- catenin and MEK/ERK/Slug signaling pathways, thereby promoting further deterioration of intrahepatic cholangiocarcinoma (ICC)." (PMID 41256854, 2025).
knee osteoarthritis (1 paper, 2016). "For example, the PARD3B SNP rs1207421 is reported in the GWAS catalog to be associated with “knee osteoarthritis” (reported GWAS p = 6 x 10−6)." (PMID 27508393, 2016).
preeclampsia (1 paper, 2022). Preeclampsia is a hypertensive disorder of pregnancy that is characterized by new-onset hypertension with proteinuria presenting after 20 weeks of gestation, and depending on mild or severe forms may initially present with severe headache, visual disturbances, and hyperreflexia. "PARD3B encodes Partitioning defective 3 homolog B, also known as PAR3 family cell polarity regulator beta, which is an adapter protein that may play a role in the formation or maintenance of epithelial tight junctions in kidney glomerulus and is found in the urine of preeclampsia patients." (PMID 35685441, 2022).
cancer (4 papers, 2017 to 2025). A tumor composed of atypical neoplastic, often pleomorphic cells that invade other tissues. "In contrast, levels of AR and PARD3B mRNAs in most of TCGA cancer types were downregulated compared to their respective normal tissues." (PMID 36013056, 2022). "In contrast, levels of AR and PARD3B mRNA in most TCGA pan-cancer types were downregulated compared to their respective normal tissues." (PMID 36013056, 2022).
neurological disorders (2 papers, 2017 to 2019). "Additionally, genes previously associated with neurological disorders were similarly up regulated, such as Mdga2, Clu, Epha3, Chl1, Cntn4, Cdh23, and Pard3b." (PMID 30628890, 2019).
PARD3B also shares sentences with these, for which no sentence is quoted: tumor (3 papers); prostate carcinoma (2); adenocarcinoma (1); adenoma (1); amyotrophic lateral sclerosis (1); breast invasive carcinoma (1); CNS embryonic tumors (1); colon adenocarcinoma (1); diabetes (1); gastrointestinal tumors (1); hand osteoarthritis (1); Hypertension (1); intestinal tumors (1); lentivirus infection (1); metabolic syndrome (1); psychiatric diseases (1); Talipes equinovarus (1).